TNF (tumor necrosis factor)
Diseases named in the same sentence as TNF in open-access papers (continued):
Sharing a sentence is not in itself a finding about the gene and the disease.
osteoarthritis (continued). "Increased interleukin 1 beta (IL-1ß), interleukin 6 (IL-6), tumor necrosis factor-alpha (TNF-α) and prostaglandin E2 (PGE2) levels in synovial fluid are seen in internal derangements of TMJ such as anterior disc displacement and osteoarthritis." (PMID 25662545, 2015). "TNFα, IL-1β and other pro-inflammatory cytokines can upregulate NOS in chondrocytes and synovial cells of osteoarthritis." (PMID 22479635, 2012). "Interleukin 1β (IL-1β) and tumor necrosis factor α (TNF-α) are key cytokines that drive the production of inflammatory mediators and matrix-degrading enzymes in osteoarthritis (OA)." (PMID 22605974, 2012). "Our results demonstrate that the signaling through TLR-4 is a proinflammatory mechanism in osteoarthritis that drives the upregulation of MMP-3, IL-1β, and TNF-α gene expression, leading to cartilage degradation and inflammation." (PMID 23118784, 2012). "We therefore hypothesize that during the 'biosynthetic phase' in early osteoarthritis, the observed increases in proteoglycan and collagen synthesis may be due to a small increase in cellular ceramide triggered by circulating cytokines such as TNF-α via activation of PKR." (PMID 16696862, 2006). "In the context of osteoarthritis, O2-O3 therapy acts as a modulator of the inflammatory response, promoting the production of TNF-β while reducing levels of pro-inflammatory cytokines, such as TNF-α and IL-8." (PMID 40427076, 2025). "Although there is no consensus about the effects of smoking on osteoarthritis (OA), the increase in TNF-alpha in smokers has been considered an important factor in OA induction or progression." (PMID 40214444, 2025). "For instance, TA could reduce the cytokine expression of IL6, IL1β, and TNFα in BV2 microglial cells, human osteoarthritis chondrocytes, in mouse models of ulcers and IL1β in BMDMs." (PMID 40565042, 2025). "KEGG enrichment analysis showed that puerarin ferroptosis-osteoarthritis common genes were mainly involved in VEGF signaling pathway, IL-17 signaling pathway, C-type lectin receptor signaling pathway, HIF-1 signaling pathway, and TNF signaling pathway." (PMID 37548663, 2024). "Furthermore, a substantial decrease was observed in the mRNA expression of inducible nitric oxide synthase, cyclooxygenase-2, 5-lipoxygenase, IL-6, TNF-α and MMP-3 and -13, thereby indicating promising therapeutic implications for osteoarthritis." (PMID 38542192, 2024). "We previously reported that the plasma endo-EV concentrations of TNF-α and IFN-γ, but not the corresponding exo-EV cytokine concentrations, were associated with knee radiographic progression of osteoarthritis, a common age-related disease." (PMID 38633262, 2024). "As for osteoarthritis and DM, the top 5 most related genes were INS, TNF, IL-6, CRP, and IL-1B." (PMID 35719662, 2022). "What is more, the expression of ADAMTS4 genes in the culture of synoviocytes from synovial tissues obtained from patients with osteoarthritis was significantly inhibited by ETA, and much more strongly inhibited when the TNF-α inhibitor was combined with a neutralizing anti-IL-1β antibody." (PMID 35407621, 2022). "This also leads to the second limitation that the in vitro stimulation with TNFα does not perfectly resemble the inflammatory components of osteoarthritis." (PMID 35892757, 2022). "Decreased GDF5 expression in cartilage could lead to chronic arthritis in TNF-transgenic mice, whereas inflammatory conditions might influence GDF5 expression via fibroblasts (inflammatory infiltration indicator) in osteoarthritis." (PMID 34210342, 2021). "Additionally, serum levels of both TNFα and OPG were higher in osteoarthritis patients compared to healthy patients." (PMID 34924815, 2021). "Additionally, luteolin can effectively reduce proliferation of osteoarthritis cartilage cells, suppress the expression of JNK and p38 in cartilage cells, and inhibit the production of NO, TNF-α, and IL-6." (PMID 33799767, 2021).
osteoarthritis (continued). "In conclusion, in contrast to the recognized proinflammatory processes mediated by neutrophils, we disclose, here, that microvesicles derived from TNFα-stimulated human neutrophils can down-regulate cytokine and chemokine expression by FLS isolated from patients with osteoarthritis." (PMID 34299030, 2021). "The serum PGE2, IL-1β, IL-6, and TNF-α levels were higher in rats with MIA induced osteoarthritis; however, these levels were suppressed in FJH-KO supplemented rats with MIA-induced osteoarthritis compared with those in rats with MIA-induced osteoarthritis (p < 0.05)." (PMID 33233504, 2020). "Furthermore, the mRNA expression of inflammatory mediators COX-2, IL-1β, TNF-α, and NF-κB was significantly decreased in the FJH-KO supplemented rats compared with that in rats with MIA induced osteoarthritis (p < 0.05)." (PMID 33233504, 2020). "Quantification of active/cleaved caspase-3 by ELISA demonstrated that TNF-α did not induce apoptosis either in HA or in osteoarthritis fibroblast-like synoviocytes." (PMID 31261789, 2019). "In the 12 patients presenting with synovitis, capsulitis, or osteoarthritis, there were elevated secreted TNF-alpha levels in synovial fluid relative to non-inflammatory controls." (PMID 31603905, 2019). "The improvement in osteoarthritis symptoms in OVX-OA-RAFR decreased the mRNA expression of matrix metallo-proteinase-1 and matrix metalloproteinase-13, tumor necrosis factor-α, and interleukin-1β and interleukin-6 in the articular cartilage compared to OVX-OA rats." (PMID 31262076, 2019). "Moreover, differentiation into osteoclasts was also found to be induced by tumor necrosis factor alpha (TNF-α), through activating of the NF-κB pathway, which particularly occurs during osteoarthritis." (PMID 30061878, 2018). "Additionally, geniposide markedly suppressed the expression of IL-1, TNF-α, NO, and MMP-13 in the synovial fluid from the rabbits with osteoarthritis." (PMID 29682561, 2018). "What is more, Huang's study showed that both EA and massage can effectively suppress the release of synovial IL-β and TNF-α in KOA of rabbits, which may contribute to the effects of acupuncture in the treatment of osteoarthritis." (PMID 30515231, 2018). "Notably, inhibition of TNF-α and LRG1 activity by Lenalidomide, an inhibitor of TNF-α production, in ACLT mice attenuated degeneration of osteoarthritis articular cartilage." (PMID 28358372, 2017). "Inflammatory cytokines such as interleukin-1 beta (IL-1β), interleukin-6 and tumor necrosis factor-alpha (TNF-α) produced by activated synoviocytes, mononuclear cells or by articular cartilage itself are strongly related to the pathophysiology of osteoarthritis." (PMID 28977876, 2017). "Previously proposed mechanisms for the protective effect of nicotine on cartilage in an early osteoarthritis rat model were reduction of the serum level of TNF-α, reduction of the expression of TNF-α in the synovial tissue, and increase in the expression of α7nAChR in the synovial tissue." (PMID 27110800, 2016). "Osteoarthritis is a multi-factorial disease process driven by the master regulators of cellular/ECM destruction, IL-1β and TNFα, pro-inflammatory molecules such as the COX-2-dependent cartilage-destructive enzyme prostaglandin E2 (PGE2), IL-6, IL-8, and the ECM-degrading enzymes such as the MMPs." (PMID 27255741, 2016). "In this work a linear regression model including age, vitamin intake, osteoarthritis, frailty phenotype, and tumor necrosis factor alpha (TNF-α) explained that the change in DHA/arachidonic ratio, TNF-α, and selenium intake had the major contribution to the observed change in walking speed." (PMID 25243159, 2014). "After resveratrol treatment, no changes in TNFα or IL-8 levels were found, but a significant dose-dependent increase in IL-6 levels was demonstrated in patients with osteoarthritis, but not controls." (PMID 23844973, 2013).
osteoarthritis (continued). "Our previous in vitro data on WIN-34B has shown cartilage protective effects through the regulation of matrix proteinases (aggrecanases and MMPs/TIMPs), inflammatory mediators (PGE2, NO, IL-1β, and TNF-α), and the MAPK pathways in osteoarthritis human cartilage explants culture and chondrocytes." (PMID 23983790, 2013). "Inflammation associated with synovial expression of TNFα is a recognised feature of osteoarthritis (OA), although no studies have yet reported beneficial effects of anti-TNFα therapy on clinical manifestations of inflammation in OA." (PMID 23036475, 2012). "This is in agreement with an animal study that reported an increase in markers of osteoarthritis in dogs with acetabular dysplasia (including IL-1β, IL-6, tumor necrosis factor (TNF)-alpha, and matrix metalloproteinase (MMP)-3) in comparison to normal dogs." (PMID 20367415, 2010). "In osteoarthritis, BROM reduces symptoms by inhibiting the expression of pro-inflammatory cytokines, including interleukin-1β (IL-1β), IL-6, monocyte chemoattractant protein-1 (MCP-1), and TNF-α, which contribute to inflammation, cartilage degradation, and joint tissue damage." (PMID 40430897, 2025). "In conclusion, l-carnitine augmented the probenecid’s anti-inflammatory effect to attenuate MIA-induced osteoarthritis in rats by provoking the miRNA-373 level and inhibiting the P2X7/NLRP3/NF-κB milieu, leading to the suppression of serum inflammatory cytokines: IL-1β, IL-18, IL-6, and TNF-α." (PMID 37994991, 2024). "Tumor necrosis factor-alpha (TNF-α), one of the pro-inflammatory cytokines mediating the local inflammatory process in joints, inhibits cartilage formation and has a detrimental effect on stem cell-based cartilage regeneration for the treatment of osteoarthritis (OA)." (PMID 37312126, 2023). "However, our finding was partially supported by previous studies suggesting that the level of TNF-α in CSF do not increase in patients with complex regional pain syndrome and post-traumatic osteoarthritis." (PMID 35061744, 2022). "Also, CEP could reverse the reduced level of cellular autophagy in IL-1β or TNF-α–induced chondrocytes, indicating that the protective effect of CEP on osteoarthritis was achieved by restoring MAPK/NF-κB-mediated autophagy." (PMID 35800437, 2022). "TGF-β1 but not BDNF, TNF-α, or IL-8 may be an important biological indicator in the CSF of osteoarthritis patients with chronic pain." (PMID 35061744, 2022). "Our data represented that at the end stage of osteoarthritis, the levels of TNF-α and IL-8 in the plasma and CSF may not be the significant physiological indicators of pain." (PMID 35061744, 2022). "Recently, increasing studies have uncovered that in diabetic patients with osteoarthritis, diabetic treatment such as DPP-4 could partially improve osteoarthritis symptoms by decreasing the production of inflammatory cytokines such as IL-6, IL-8, and TNF-α." (PMID 35719662, 2022). "This study aimed to determine whether hesperetin (HPT) has chondroprotective effects against the TNF-α-induced inflammatory response of chondrocytes and related mechanisms and clarify the impact of HPT on osteoarthritis (OA) induced by anterior cruciate ligament transection (ACLT)." (PMID 34603050, 2021). "However, the role of visfatin in IL-6 and TNF-α production in osteoarthritis synovial fibroblasts (OASFs) has not been extensively studied." (PMID 29316707, 2018). "ACS for treatment of osteoarthritis contains increased levels of anti-inflammatory as well as pro-inflammatory cytokines, in particular TNF-α, but conditioned serum does not seem to have a net direct effect on cartilage metabolism, even upon inhibition of TNF-α." (PMID 20537160, 2010).
osteoarthritis (continued). "However, in chronic diseases such as osteoarthritis, non-alcoholic steatohepatitis, and Brucella abortus infection, GPR84 plays a role in modulating inflammation by reducing the expression of pro-inflammatory factors (such as TNF-α), thereby alleviating disease progression or promoting infection." (PMID 39858878, 2025). "Moreover, IL-1β and TNFα also stimulate the synthesis of prostaglandins, nitric oxide, phosphatidylinositol 3-kinase (PI3K)/protein kinase B (Akt), nuclear factor κB (NF-κB), and diverse mitogen-activated protein kinase (MAPK) signaling pathways further contributing to osteoarthritis pain." (PMID 31905764, 2019). "Some recent studies suggest as therapeutic agents disease-modifying osteoarthritis drugs (DMOAD) and some targeting therapies against inflammatory mediators such as IL1, IL6, or TNFα; however, they are not officially recognized." (PMID 37109424, 2023). "Our data show that FJH-KO supplementation in rats with MIA-induced osteoarthritis significantly decreased the serum levels of PGE2, IL-1β, and TNF-α compared with those in rats without FJH-KO supplementation." (PMID 33233504, 2020). "The expression of TNF-α, TNF-R1, and TNF-R2 was strongly increased in HA synovium (n = 10) compared to the non-inflamed osteoarthritis control synovium (n = 8), as assessed by both immunohistochemistry and Western blotting." (PMID 31261789, 2019). "There were no changes in pro-inflammatory cytokines levels: tumor necrosis factor-alpha (TNF-α), interferon-γ (IFN-γ), and IL-12 (p70)) after the 21-day general rehabilitation, indicating the stable and controlled inflammatory status of osteoarthritis patients." (PMID 35625533, 2022). "Stimulation with TNF-α resulted in a significant increase in HA fibroblast-like synoviocyte proliferation quantified by the water-soluble tetrazolium (WST)-1 assay, while it had no relevant effect on osteoarthritis fibroblast-like synoviocytes." (PMID 31261789, 2019). "Moreover, the treatment with osteotropic factors, such as vitamin D3, IL‐1β, TNF‐α, PGE2, IL‐6, but not PTH, and IL‐17, has been correlated with an increased membranous localization of RANKL on low osteoarthritis osteoblasts compared with high osteoarthritis osteoblasts." (PMID 28425564, 2017).
lung carcinoma (486 papers, 2000 to 2026). "This suggests it regulates the lung microenvironment via the “gut-lung axis”, e.g., by reducing pro-inflammatory cytokines (TNF-α, IL-6) and lowering lung cancer risk." (PMID 41003841, 2025). "This meta-analysis aims to clarify the association between the TNF-α -308G > A and − 238G > A polymorphisms and lung cancer risk." (PMID 39243014, 2024). "Overall, evidence indicates that the TNF-α -238G > A polymorphism plays a nuanced role in lung cancer risk influenced by genetic and demographic factors." (PMID 39243014, 2024). "Overall, the evidence indicates that the TNF-α -308G > A polymorphism plays a complex role in lung cancer risk, driven by ethnicity and cancer subtype." (PMID 39243014, 2024). "To date, several aggregated articles published between 2011 and 2017 have examined the link between TNF-α -308G > A and − 238G > A polymorphisms and lung cancer risk." (PMID 39243014, 2024). "Researchers conducted a study on tumor necrosis factor (TNF) and discovered that higher levels of TNF were linked to an increased risk of coronary artery disease, while lower levels of TNF were connected with a decreased risk of lung cancer." (PMID 39668834, 2024). "The pooled analysis of TNF-α polymorphisms − 308G > A and − 238G > A reveals significant variability in lung cancer risk across populations and cancer types." (PMID 39243014, 2024). "Similar with our results, elevated levels of TNF-α have been considered to be linked to an increased risk of lung cancer." (PMID 38813211, 2024). "In the oral surveillance study, RA patients aged ≥50 years with one additional cardiovascular risk factor who were receiving tofacitinib 10 mg two times daily had an increased risk for lung cancer compared with those receiving TNF inhibitors." (PMID 39458207, 2024). "In our study, we found that TNF-α alone as a diagnostic biomarker for lung carcinoma lacks sufficient sensitivity (70.5 %) and specificity (77.5 %)." (PMID 38813211, 2024). "Despite challenges from diverse methodologies, the analysis confirmed a stable association between TNF-α polymorphisms and lung cancer susceptibility." (PMID 39243014, 2024). "Overall, the TNF-α -238G > A polymorphism highlights variations in lung cancer risk across different populations and cancer types, revealing both risk and protective effects based on genotype." (PMID 39243014, 2024). "In support of distinct T cell populations driving irAEs, within a cohort of thymic and lung cancers, 4 distinct subtypes of T cells were associated with irAEs: Th17 related, TNF related, and 2 Treg clusters." (PMID 39403935, 2024). "The analysis of TNF-α -308G > A and − 238G > A polymorphisms in relation to lung cancer risk presents both strengths and weaknesses." (PMID 39243014, 2024). "To resolve the debate regarding the associations of TNF-α -308G > A and − 238G > A polymorphisms with lung cancer risk, we undertook this meta-analysis by identifying all relevant studies." (PMID 39243014, 2024). "Insufficient data for stratified analyses regarding confounding factors, including age, gender, smoking habits, and lung cancer types, limits the evaluation of their influence on TNF-α polymorphisms and lung cancer risk." (PMID 39243014, 2024). "The evaluation of TNF-α polymorphisms and their association with lung cancer susceptibility showed significant heterogeneity for the TNF-α -308G > A polymorphism." (PMID 39243014, 2024). "Sensitivity analysis evaluated the stability of the link between TNF-α polymorphisms and lung cancer susceptibility, showing that both overall and stratified outcomes remained statistically robust despite variations in study inclusion." (PMID 39243014, 2024). "For instance, TNF-α, despite its anti-tumor properties, has long been implicated in the development of various cancers, including lung cancer, gastric cancer, pancreatic cancer, and liver cancer." (PMID 38813211, 2024).